PML (PML nuclear body scaffold)
Diseases named in the same sentence as PML in open-access papers (continued):
Sharing a sentence is not in itself a finding about the gene and the disease.
breast carcinoma (continued). "The quantification of the relative relevance of each PML effector pathway in the overall activity of PML could open new opportunities to apply the biology of PML-regulated TNBC function for breast cancer treatment." (PMID 31570853, 2020). "To date, glioma and a subset of breast cancers exhibit PML-dependent self-renewal activity, whereas other tumors, such as ovarian cancers or some experimental models of hepatocarcinoma development, exhibit a broad tumor suppressive response upon PML inhibition." (PMID 31570853, 2020). "To further investigate the hypothesis that FOXM1 is a downstream signaling target of PML in breast cancer, we studied the effect of PMIV induction on FOXM1 protein and mRNA expression levels over a 48‐h time course." (PMID 30927552, 2019). "Exploration of this novel ‘ERβ-PML-(Foxo3a/Survivin)’ signaling axis might hopefully provide a new direction in the clinical management of breast cancer." (PMID 31506431, 2019). "However much less is known about the transcriptional regulation of PML, more so in the context of breast carcinoma." (PMID 31506431, 2019). "In this study, we addressed the role of PML in breast cancer cells." (PMID 30927552, 2019). "Also, PML has been proposed to contribute to the tumorigenesis of triple negative and basal-like breast cancers which resemble breast stem/progenitor cells." (PMID 29416846, 2018). "In addition, PML expression is required for survival of hematopoietic stem cells and breast cancer stem cells through activation of PPAR-δ pathway." (PMID 26510911, 2015). "It was reported that in breast cancer cell lines Pin1 binds PML, inducing its downregulation." (PMID 23526763, 2013). "It will be critical to define the PML profile in these breast cancers where gain of pro-survival functions is apparent and fascinating to explore whether PML targeted therapy such as As2O3 has an application in these specific cancers." (PMID 23730625, 2013). "But PML also serves as a regulator of acetylation events, as revealed in a study that uncovered the contribution of PML for enhanced fatty acid oxidation in metabolically hyperactive breast cancer cells." (PMID 23293771, 2012). "Furthermore, senescence suppression by TBX2 in human cells depends on the physical interaction of TBX2 with tumor suppressive TFs, for example EGR1 in breast cancer cells, and PML in fibroblasts." (PMID 22844464, 2012). "Previous studies have shown that the knockdown of PML inhibits the proliferation of oestrogen receptor-positive breast cancer cells and promotes the expression of oestrogen receptor target genes, thereby increasing oestrogen receptor-positive breast cancer cell stemness." (PMID 39824883, 2025). "Notably, SP100 is responsible for the formation of PML nuclear bodies, predominantly serving as a suppressor of tumorigenesis across various cancer types, encompassing melanoma, glioblastoma, leiomyosarcoma, breast cancer, and laryngeal cancer." (PMID 38118002, 2024). "Besides, the promyelocytic leukemia (PML) gene encodes for a tumor suppressor protein that potentiates PGC-1α deacetylation through SIRT1, thus promoting bioenergetics and protection against anoikis in breast cancer." (PMID 29629336, 2018). "PML overexpression was confirmed also in glioblastoma multiforme (GBM) and breast cancer (BRCA), albeit being more evident in ccRCC." (PMID 38730056, 2024). "The intersection of the two datasets manifested 2 potential targets for HER2-positive breast cancer, zinc finger and BTB/POZ domain-containing family protein 16 (ZBTB16) and promyelocytic leukemia protein (PML), which are known as essential tumor suppressors." (PMID 38110365, 2023). "The PML-RARA fusion gene is related to acute ovarian cancer, and RARA participates in estrogen signal transmission and is the target gene of estrogen in breast cancer." (PMID 35051904, 2022).
breast carcinoma (continued). "Another study found that PML can promote the expression of SOX9 and thus enable breast cancer cells to acquire cancer-initiating cells (CIC) properties." (PMID 33968766, 2021). "Altogether, our results provide a feasible explanation for the functional similarities of MYC, PIM1, and PML in TNBC and encourage further study of PML targeting strategies for the treatment of this breast cancer subtype." (PMID 31570853, 2020). "We considered breast cancer SK-BR-3 and MCF-7 cells, lung cancer A-549 cells as well as APL-derived and PML-RARα+NB4 blasts which synthesize measurable levels of S100A3 and RARα." (PMID 30532072, 2019). "Among these PML targeting genes, ITGB1 mRNA and protein levels are up-regulated in PML knockdown HUVECs and MDA-231 breast cancer cells." (PMID 29416846, 2018). "Instead of directing flows with cell cycle regulators as in the case of breast cancer, there are in general uncoordinated functions between RB1 with transcriptional regulators LMO2 and PML and RFC1 that regulate DNA replication." (PMID 26975659, 2016). "Consistently, the phosphorylation-mimetic mutant SATB1S47D is reluctant to be localized to PML body, whereas the mutant SATB1S47A is unstable in several breast cancer cell lines." (PMID 23762260, 2013). "Of note, this analysis showed similar levels of PML protein across ccRCC, breast cancer and glioblastoma multiforme specimens, unlike cell lines, where PML upregulation was more evident in ccRCC." (PMID 38730056, 2024). "PML depletion reduces cell proliferation, invasion, and stemness, while heterologous PML1 expression augments these processes and fuels tumor growth and resistance to fulvestrant, an FDA-approved drug for ER + breast cancer, in a mouse model." (PMID 37720048, 2023). "The data produced by us and others argue in favor of a molecular make up in this subtype of breast cancer that requires the presence of PML in high doses, as opposed to estrogen receptor-positive tumor cells." (PMID 31570853, 2020). "PML acting as a tumor suppressor in vivo inhibited normal cell apoptosis and differentiation, and it could regulate tumor suppressor FOXO3 to suppress the growth of breast cancer cells." (PMID 38750402, 2024). "Therefore, the use of PML-targeting drugs that activate proteasomal degradation could be of remarkable interest in the treatment of CML and breast cancer." (PMID 23936764, 2013). "PML is upregulated in metastatic breast cancer and non-metastatic breast cancer with a poor prognosis, and studies indicate that PML may be involved in expression of the stem cell factor SOX9 and associated initiation of breast cancer." (PMID 33324553, 2020). "ATRA treatment of MCF-7 breast cancer cells reduced p11 but not p36 transcript and protein levels, thus indicating that ATRA can regulate p11 levels independently of PML/RARα and p36." (PMID 30206209, 2018).
HCMV infection (25 papers, 2007 to 2025). "It has been demonstrated that transcription of mRNA encoding PML and other anti-viral proteins in PML bodies is stimulated by the presence of IFNβ during HCMV infection." (PMID 38063292, 2023). "Therefore, the canonical SCM-specific SUMOylation allows UL44 protein to co-localize with ND10 structures through its association with the PML factor during HCMV infection." (PMID 34747321, 2021). "Since PML directly interacts with HDAC1 and HDAC2, which may affect ISG transcription, we also assessed whether PML associates with these HDACs after UV-HCMV infection." (PMID 25812002, 2015). "Furthermore, we found that during HCMV infection IE1 reduced the association of PML, STAT2, and HDAC1 with ISG promoters." (PMID 25812002, 2015). "HCMV infection stimulates degradation restriction factors including Daxx, PML, and BclAF1 (10, –, 12, 38)." (PMID 39655950, 2025). "In cells permissive to HCMV infection, PML and Sp100 act as cellular restriction factors by inhibiting viral IE gene expression." (PMID 37058447, 2023). "As a major finding, our data provide evidence that PML can enclose both input viral genomes and newly assembled nuclear capsids, which are distinguishable activities occurring at different times of HCMV infection." (PMID 35319461, 2022). "Overall, these data indicate a dual, PML-based inhibition of HCMV infection and suggest entrapment of viral material as a general restriction mechanism used by PML-NBs." (PMID 35319461, 2022). "Taken together, we show a multilayered antiviral role of PML-NBs during HCMV infection, which is based on an entrapment mechanism likely leading to a more efficient inhibition or immobilization of viral components." (PMID 35319461, 2022). "Upon HCMV infection, PML-NBs sense and entrap viral genomes entering the nucleus and induce epigenetic silencing of the viral DNA by recruiting chromatin-modifying enzymes." (PMID 36233232, 2022). "Upon HCMV infection, PML-NBs target viral genomes entering the nucleus and restrict viral immediate–early gene expression by epigenetic silencing." (PMID 36233232, 2022). "It was shown that HCMV infection induces the disruption of promyelocytic leukemia (PML) nuclear bodies and PML bodies are involved in controlling HSV-1 latency, suggesting a possible factor contributing to the induction of reactivation by HCMV." (PMID 35862979, 2022). "The impact of PML-NBs on lytic HCMV infection has been characterized by numerous studies in primary human fibroblasts, which revealed an inhibitory effect of the main NB components PML, Sp100, Daxx and ATRX on viral immediate–early (IE) gene expression." (PMID 36233232, 2022). "Upon HCMV infection of HFF cells, the IE1 protein leads to a rapid loss of SUMOylated PML and to a disruption of PML-NBs." (PMID 36233232, 2022). "In summary, our data demonstrate a cell type-specific effect of PML-NB components on lytic HCMV infection and suggest an important role of PML in the inhibition of HCMV dissemination through infected endothelial cells." (PMID 36233232, 2022). "Next, we sought to find what contributes to the co-localization of UL44 and PML during HCMV infection." (PMID 34747321, 2021). "Several of our conclusions should also be more broadly relevant to cellular events beyond hCMV infection given the versatile roles of PML and PML bodies in health and disease." (PMID 32365141, 2020). "Having said that, our findings suggest that interactions with STAT family members via the SBM contribute more significantly to IE1 function during productive hCMV infection than PML interaction, especially at higher MOIs." (PMID 32365141, 2020). "In accordance with this immunofluorescence experiment, protein levels, as measured on western blots, of PML itself and of the PML NB components Sp100 and Daxx, decreased after HCMV infection, but increased after KSHV infection of primary endothelial cells." (PMID 31059555, 2019).
HCMV infection (continued). "Upon Human Cytomegalovirus (HCMV) infection, the HCMV IE1 protein associates with PML and inhibits PML-bound Stat1 and Stat2 activity, resulting in low ISG expression and reduced innate immunity." (PMID 29416846, 2018). "LUNA transfection promoted dispersal of PML bodies, and furthermore, latent HCMV infection promoted PML body dispersal in a LUNA-dependent manner." (PMID 30021158, 2018). "In human cytomegalovirus (HCMV) infections, immediate-early (IE) 1 protein interacts with PML and disrupts PML NBs." (PMID 25812002, 2015). "To investigate the mechanism by which PML promotes ISG transcription, we compared levels of IRF3, STAT1, STAT2, and their activated forms in control and PML-knockdown HF cells after UV-HCMV infection." (PMID 25812002, 2015). "PML was required for accumulation of activated STAT1 and STAT2, interacted with them and HDAC1 and HDAC2, and was associated with ISG promoters after HCMV infection." (PMID 25812002, 2015). "A key feature of the IE1 protein appears to be its ability to target to and disruptsubnuclear multi-protein structures known as PML bodies or ND10 during the earlyphase of hCMV infection and upon ectopic expression." (PMID 21533215, 2011). "Importantly, this phenotype can be rescued by overexpressing PML, confirming the direct participation of the SOX2-PML axis in regulating HCMV infection." (PMID 37058447, 2023). "The anti-viral role of PML bodies in response to type I interferon proteins has been previously investigated, showing that an increase in mRNA encoding the HCMV inhibitory proteins, including PML, in response to IFNβ produced from cells upon HCMV infection." (PMID 38063292, 2023). "Together, these data strongly supported our hypothesis that SOX2 downregulated PML expression to facilitate HCMV infection and viral gene expression, consequently promoting glioma growth." (PMID 37058447, 2023). "This gives ground to assume that, after initial disruption of PML-NBs, IE1 remains bound to PML in order to antagonize capsid entrapment at late stages of HCMV infection and may explain the metabolic stability of the immediate-early protein." (PMID 35319461, 2022). "To corroborate this finding, we analyzed whether inhibition of DNA damage signaling affects the formation of PML cages in the context of HCMV infection." (PMID 35319461, 2022). "Finally, our data suggest an important inhibitory role of PML in HCMV infection of endothelial cells and, consequently, for viral dissemination and development of vascular disease." (PMID 36233232, 2022). "While the impact of PML-NBs on lytic HCMV infection has been extensively studied in fibroblasts, their role in endothelial cells, which promote the spread of HCMV in vivo, remains unknown." (PMID 36233232, 2022). "In line with this, we detected the chromosomal DNA-binding protein HP1α (heterochromatin protein 1 alpha) at PML cages, which is involved in establishing a stable heterochromatic structure and is usually excluded from replication centers during wild-type HCMV infection." (PMID 35319461, 2022). "Here, we describe unusually large PML-NBs, referred to as PML cages, which have the capacity to entrap both parental viral genomes and newly assembled viral capsids thus contributing to the restriction of human cytomegalovirus infection." (PMID 35319461, 2022). "Upon HCMV infection, Daxx is initially targeted for degradation by the viral tegument protein pp71; however, it re-accumulates at later stages of infection and can be detected at PML cages (Saffert and Kalejta, 2006)." (PMID 35319461, 2022). "Moreover, immunofluorescence localization analyses on the wt-HCMV infection showed that upon interference of endogenous PML by siPML, the UL44-wt distribution, as well as that of PIAS3, turned from the nuclear foci to nuclear extensive diffusion (ix versus x)." (PMID 34747321, 2021).
HCMV infection (continued). "It would also be interesting to investigate whether the individual PML isoforms are differentially dispersed in HCMV infection and to examine their consequences." (PMID 33546431, 2021). "Although early studies generated models in which PML-NBs were acting in a pro-viral manner to support HCMV infection, there were also data indicating that PML-NB proteins could possibly be antiviral." (PMID 32226778, 2020). "Furthermore, after UV-HCMV infection, PML formed a protein complex with STAT1, STAT2, HDAC1, and HDAC2 and associated with ISG promoters." (PMID 25812002, 2015). "Furthermore, reduction of PML expression increases permissivity of human cells to human cytomegalovirus infection, and over-expression of PML reduces permissivity to vesicular stomatitis virus and influenza A." (PMID 17565686, 2007). "In addition, SOX2-OE enhanced the oncomodulatory activities of HCMV infection, which could be offset by induced PML expression." (PMID 37058447, 2023). "Interestingly, PML depletion from HEC-LTT not only enhanced viral IE gene expression after low multiplicity infection but also promoted HCMV infection with higher virus doses, which usually leads to a saturation of restriction factors so that antiviral effects are no longer detectable." (PMID 36233232, 2022). "Since during HCMV infection, the immediate-early protein IE1 functions as inhibitor of interferon (IFN) signaling, we hypothesized that the drastic enlargement of PML-NBs after infection with IE1-deficient HCMV results from IFN-mediated upregulation of PML-NB proteins." (PMID 35319461, 2022). "The IE1-PML interaction was associated with enhanced rather than reduced expression of cytokines and interferon stimulatory genes (ISGs), suggesting that disruption of PML by IE1 contributes to the antiviral and proinflammatory response during HCMV infection." (PMID 40143325, 2025). "A novel antiviral role for PML-bodies recently observed during human cytomegalovirus (HCMV infection), using correlative light and transmission electron microscopy (CLEM), is the restriction of viral capsids by cage structures formed by PML-NBs." (PMID 41305450, 2025). "Among these candidates, five host factors (PML, Sp100, ISG15, IRP9, and RSAD2) have been related to HCMV infection and were further investigated." (PMID 37058447, 2023). "Depletion of individual PML-NB proteins by lentiviral transduction revealed an exceptionally strong antiviral effect of PML in HEC-LTT cells, whereas Daxx was found to promote HCMV infection." (PMID 36233232, 2022). "This is in accordance with Western blot analysis of PML-knockdown and control HEC-LTT, which revealed a comparable accumulation of IE1 and IE2 in the first 24 h upon HCMV infection." (PMID 36233232, 2022). "Previous studies of our and other groups have shown that IE1 blocks IFN signaling during HCMV infection by affecting both STAT proteins and PML, which has been identified as positive regulator of IFN-induced gene expression." (PMID 35319461, 2022). "While HCMV infection leads to a diffuse distribution of PML staining, infection of HUVECs with KSHV significantly increased the number of discrete PML NBs in infected cells in comparison to uninfected cells." (PMID 31059555, 2019). "Similarly, during human cytomegalovirus (HCMV) infection, the viral immediate early protein 1 (IE1) binds to the coiled-coil domain of TRIM19/PML." (PMID 40354393, 2025). "For HCMV infections, however, such a dynamic behavior of PML-NBs has not been observed and sensing appears to be rather inefficient, when more than one genome is present in a cell nucleus." (PMID 36233232, 2022). "To characterize the repressive effects of PML-NBs further, we analyzed their role during HCMV infection in absence of the antagonistic activity of IE1." (PMID 35319461, 2022). "As opposed to Sp100 merely being used as a PML-NB marker assumed to behave as PML, this section focuses on Sp100 isoforms during HCMV infection." (PMID 33598438, 2020).